FJX1 (four-jointed box kinase 1)
Diseases named in the same sentence as FJX1 in open-access papers (continued):
Sharing a sentence is not in itself a finding about the gene and the disease.
tumor (8 papers, 2013 to 2025). "Positive correlations were found between FJX1 expression and tumor-associated macrophages (TAMs) and with immune-related genes such as TGFB1 and IL-10 and immunosuppressive pathway-related genes such as TGFB1 and WNT1." (PMID 37324001, 2023). "Thus, our data indicate that overexpression of FJX1 by tumor cells is associated with increased secretion of other pro-angiogenic factors contained within the flow-through fraction." (PMID 23922772, 2013). "Thus, genetic deletion of endogenous FJX1 in mice results in inhibition of colonic tumorigenesis in association with reduced tissue angiogenesis, consistent with the increase in tumor vasculature observed in SW480FJX1MYC cells grown as xenografts." (PMID 23922772, 2013). "The immunogenicity of FJX1, when targeted by DNA-based vaccines, leading to efficient tumor clearance independently or with anti-PD1, highlights its potential as a vaccine target." (PMID 39136024, 2024). "The relationship between FJX1 expression and immune-related genes and immunosuppressive pathway-related genes was analyzed using The Tumor Immune Estimation Resource version 2 (TIMER2)." (PMID 37324001, 2023). "Our research findings demonstrate that FJX1 is a new prognostic factor with a significant role in tumor immunity." (PMID 37324001, 2023). "We also found that FJX1 expression is positively associated with TGFB1 and IL-10, which can induce macrophages to M2 polarization and regulate tumor immunology." (PMID 37324001, 2023). "FJX1 affects tumor cell proliferation and differentiation as a downstream target gene of the Notch signaling system." (PMID 35928453, 2022). "FJX1 protein levels in the tumor were higher than in normal tissue, while KLHL35 protein levels were undetectable in both tumor and normal tissues, and no immunohistochemistry data for the remaining two genes were available." (PMID 35928453, 2022). "The logFC in the volcanic diagram is greater than 1, indicating that FJX1 is most likely the determining factor in tumor spread." (PMID 35928453, 2022). "We subsequently examined the protein expression of MAGED4B and FJX1 in HNSCC tumour tissues from both Malaysian and UK cohorts by IHC." (PMID 34733290, 2021). "FJX1 expression was detected in 18 of 43 (42%) of the tumours examined, consistent with our microarray and qRT-PCR observations that FJX1 is upregulated in NPC." (PMID 31236144, 2019). "In this study, we chose to design and evaluate the efficacy of short-peptides specifically targeted against FJX1, a tumor antigen that we have previously observed to be highly elevated in NPC, but low in normal nasopharyngeal tissue." (PMID 26536470, 2015). "We postulated that our observation that patients with higher FJX1 mRNA expression have worse survival outcomes is related to the functional effects of FJX1 on tumor formation." (PMID 23922772, 2013). "Taken together our results support the conclusion that FJX1 is a novel regulator of tumor progression, due in part, to its effect on tumor vascularization." (PMID 23922772, 2013). "Moreover, genes implicated in immune evasion such as FJX1 and Aldoc were also downregulated specifically in TPC2 KO cells, supporting a dual role for TPC2 in tumour proliferation and immune escape." (PMID 41209002, 2025). "The FJX1 expression increased with tumor stage in ACC, COAD, ESCA, KIRP, LUAD, and UVM." (PMID 37324001, 2023). "Although previous research suggests that high FJX1 expression is associated with poor prognosis in different tumors, the specific mechanism and role of the tumor immunosuppressive microenvironment have not been fully explored." (PMID 37324001, 2023).
tumor (continued). "The capability of FJX1-expressing cells to invade through the Transwell membrane suggests that FJX1 enhances the invasiveness of tumour cells and could contribute to the ability of tumour cells to metastasize." (PMID 31236144, 2019). "FJX1 mRNA expression is upregulated in ovarian tumor endothelial cells as compared to normal ovarian endothelial cells and thus has been suggested as a candidate tumor vasculature marker in ovarian cancer." (PMID 23922772, 2013). "In both models we found an association between vascularization and FJX1 expression; colonic sections and tumor xenografts lacking FJX1 had fewer blood vessels." (PMID 23922772, 2013). "To determine whether FJX1 expression alters xenograft tumor formation in vivo, we next injected either SW480VEC (n = 11) or SW480FJX1MYC (n = 14) cells subcutaneously on the flanks of individual athymic nude mice." (PMID 23922772, 2013). "Thus, overexpression of FJX1 affected the rate of xenograft tumor growth due primarily to differences in the rate of tumor cell proliferation." (PMID 23922772, 2013). "One potential target for immunotherapy is four jointed box 1 (FJX1), which is closely related to various tumor pathways in other species." (PMID 37324001, 2023). "The Mann-Whitney U test (Wilcoxon rank-sum test) for unpaired samples showed the expression of CSTL1, FJX1, IER5L, and KLHL35 in tumor tissue was higher than that in normal tissue." (PMID 35928453, 2022). "In addition, FJX1 expression is directly proportional to the level of infiltration of most immune cells, and the lmmuneScore increased with high FJX1 expression, suggesting that an elevation in FJX1 could trigger an inflammatory response that accelerates tumor growth." (PMID 35928453, 2022). "Among those inhibited after treatment was four jointed box one (FJX1), a unique gene with no known function in tumor biology." (PMID 23922772, 2013). "Since FJX1 enhanced tumor cell proliferation in vivo but it had no direct effect on cell proliferation in vitro, we postulated that factors associated with the tumor microenvironment and angiogenesis contributed to this discrepancy." (PMID 23922772, 2013). "Using TCGA-HNSC project data, we demonstrated that both MAGED4B and FJX1 gene expression levels in the HPV negative (n=415) and HPV positive (n=72) tumour tissue samples were significantly higher than levels in adjacent normal tissues (n=44)." (PMID 34733290, 2021). "First, mice lacking endogenous FJX1 had fewer colonic polyps after AOM/DSS treatment as compared to wild-type littermates, suggesting that FJX1 expression enhances tumor formation in vivo." (PMID 23922772, 2013). "This suggests that FJX1-specific CTL repertoire was not completely exhausted and re-sensitization of the immune system with FJX1-derived peptides may be able to reactivate the T-cells that may have been inactivated or tolerated overtime to re-recognize tumor cells." (PMID 26536470, 2015).
colonic polyps (1 paper, 2013). "Upon gross examination, FJX1 null mice had significantly fewer colonic polyps than the wild-type control mice." (PMID 23922772, 2013). "Furthermore, FJX1 null mice develop significantly fewer colonic polyps than wild-type littermates after combined dextran sodium sulfate (DSS) and azoxymethane (AOM) treatment." (PMID 23922772, 2013).
infection (1 paper, 2025). The state of being infected such as from the introduction of a foreign agent such as serum, vaccine, antigenic substance or organism. "Glypican 5 (Gpc5) is associated with processes related to neuroinflammation 38, and Four-Jointed Box Kinase 1(Fjx1) is associated with infection." (PMID 40303348, 2025).
FJX1 also shares sentences with these, for which no sentence is quoted: colorectal adenoma (1 paper); fibrosis (1); lung adenocarcinoma (1); metastasis (1); oral squamous cell carcinoma (1); prostate adenocarcinoma (1); rectal adenomas (1); rectal tumors (1); renal fibrosis (1); retinopathy of prematurity (1); sarcopenia (1); skin cutaneous melanoma (1).